ABCG2 (ATP binding cassette subfamily G member 2 (JR blood group))
Diseases named in the same sentence as ABCG2 in open-access papers (continued):
Sharing a sentence is not in itself a finding about the gene and the disease.
cancer (continued). "As well as to the well-studied multidrug resistant protein P-glycoprotein(ABCB1), the overexpression of ABCG2 results in cancer cells resistant to various chemotherapeutic drugs by extruding these compounds out of the cells, such as topotecan and methotrexate." (PMID 22870247, 2012). "Here, we show that acquired resistance of wtEGFR-expressing cancer cells to an EGFR TKI, gefitinib, is associated with elevated expression of breast cancer resistance protein (BCRP/ABCG2), which in turn leads to gefitinib efflux from cells." (PMID 21731744, 2011). "Cancer stem cells have been shown to exhibit drug resistance properties by expressing multidrug resistance genes such as ABCG2." (PMID 21304978, 2011). "Included in this list is ABCG2, an ABC transporter that has also been associated with MDR in certain cancers." (PMID 21829205, 2011). "Recent studies provide evidence that adenosine triphosphate (ATP)-binding cassette (ABC) transporter ABCG2 plays a pivotal role in regulating the cellular accumulation of porphyrins in cancer cells and thereby affects the efficacy of PDD." (PMID 24310600, 2011). "Topotacan is an established ABCG2 substrate and is currently approved for the treatment of various cancers." (PMID 21283667, 2011). "Protein kinase inhibitors are suggested to potentially enhance the PDD efficacy by blocking ABCG2-mediated porphyrin efflux from cancer cells." (PMID 24310600, 2011). "This is due to their overexpression of the ABCG2 drug resistance protein, one of the important characteristics of cancer stem/progenitor cells." (PMID 21521521, 2011). "This is one of the important properties for cancer stem/progenitor cells because of the expression of ABCG2 drug resistance protein." (PMID 21521521, 2011). "Hitherto, many attempts have been made to circumvent ABCG2-mediated multi-drug resistance of human cancer by developing ABCG2-specific inhibitors." (PMID 24310600, 2011). "It has been demonstrated that endogenous ABCG2 expression in certain cancers is a possible reflection of the differentiated phenotype of the cell of origin and likely contributes to intrinsic drug resistance." (PMID 21943250, 2011). "Taken together, ABCG2 is one of the critical factors that affect the efficacy of PDT as well as chemotherapy of human cancer." (PMID 21188243, 2010). "Human ABCG2, a member of the ATP-binding cassette transporter superfamily, plays a key role in multidrug resistance and protecting cancer stem cells." (PMID 21151870, 2010). "Protein kinase inhibitors, including imatinib mesylate and gefitinib, are suggested to potentially enhance the efficacy of photodynamic therapy by blocking ABCG2-mediated porphyrin efflux from cancer cells." (PMID 21188243, 2010). "Clearly, more specific ABCG2 inhibitors are needed for future development of potential chemo-sensitizers to better treat drug resistant cancers." (PMID 19479068, 2009). "PZ-39 is not cytotoxic itself with an IC50 of >24 μM while being very potent in sensitizing MDR of cancer cells over-expressing ABCG2." (PMID 19479068, 2009). "On the other hand, clinically attainable but non-toxic doses of vandetanib were found to significantly enhance the sensitivity of MDR cancer cells to ABCC1 or ABCG2 substrate antitumor drugs." (PMID 19390592, 2009). "In this study, we investigated a novel potent specific inhibitor of human ABCG2, PZ-39, as a potential therapeutic agent to sensitize drug resistance in cancer chemotherapy." (PMID 19479068, 2009). "Normal and cancer stem cells express transmembrane transporters, such as the ATP-binding cassette protein, ABC transporter ABCG2/BCRP1 (breast cancer resistance protein 1)." (PMID 19555472, 2009). "To investigate if PZ-39 can reverse ABCG2-mediated multidrug resistance in a drug resistant cancer cell line, we used the drug-selected MCF7/AdVp3000 cells and tested two additional anticancer drug substrates of ABCG2, Adriamycin and camptothecin." (PMID 19479068, 2009).
cancer (continued). "This suggests that ABCG2 overexpression is an early molecular marker of the development of MDR in these three cancer cell types." (PMID 18382425, 2008). "This is the first report to our knowledge of single-step, low-dose selection leading to overexpression of ABCG2 by epigenetic changes in multiple cancer cell lines." (PMID 18382425, 2008). "The ABCG2 multidrug-transporter is widely expressed in a variety of tissue stem cells and cancer stem cells, suggesting that it plays an important role in self-renewal maintenance." (PMID 19107196, 2008). "The SP sorting protocol was also used on two ABCG2+ cancer cell lines (MCF-7 and C4-2) as positive controls." (PMID 17425799, 2007). "Also, has been shown to inhibit ABCG2 EP that is one of the reasons for the development of MDR in cancer." (PMID 41321948, 2025). "Therefore, novel ABCG2 inhibitors or modulators with novel structures and/or mechanisms remain an unmet clinical need in treating ABCG2-overexpressing cancers." (PMID 40066335, 2025). "Indeed, NRF2 has lesser-known roles in binding to promoter regions and upregulating expression of the ABCB1 and ABCG2 drug efflux transporters directly impacting drug retention within cancer cells." (PMID 41372143, 2025). "Moreover, efflux transporters, such as Breast Cancer Resistance Protein, BCRP, also known as ABCG2, can expel nucleoside analogs from cancer cells, which decreases their intracellular levels, thus contributing to resistance." (PMID 40723396, 2025). "The authors of both publications concluded that a combined treatment of ABCB1 and ABCG2 substrates with abemaciclib could have a beneficial antitumor effect in multidrug-resistant cancers." (PMID 40284428, 2025). "In this work, we first disclosed the widely potent reversing effects of KSQ‐4279, a highly‐selective USP1 inhibitor currently in clinical trial (Phase I) for advanced solid tumors (NCT05240898), on ABCB1/ABCG2/ABCC1‐induced MDR cancers, and the exact mechanisms behind were elucidated." (PMID 41328326, 2025). "Furthermore, the expression of cancer stem cell-related markers—ABCG2, Bmi-1, and Nanog—was validated, confirming that SRGN enhances the self-renewal and stemness of malignant HCC cells." (PMID 40384866, 2025). "Moreover, genes related to cancer therapeutic targets, such as ABCG2, GSK3B, PTCH1, STAT3 and WEE1, were also upregulated." (PMID 39726234, 2025). "Additionally, the complexes modulate the expression of efflux transporters such as ABCG2, which contribute to drug resistance in CSCs, potentially overcoming mechanisms that aid cancer cell survival during chemotherapy." (PMID 40733139, 2025). "Moreover, these compounds enhanced the sensitivity of drug-resistant cancer cell lines to mitoxantrone, underscoring their potential to overcome ABCG2-mediated MDR." (PMID 40508176, 2025). "Besides, in SCC cells, TGF-β can activate the AKT pathway, followed by overexpression of SOX2 and ABCG2, which are characteristic of cancer stem cells, indicating the ability to induce cancer cell dedifferentiation that corresponds to cisplatin resistance." (PMID 40486962, 2025). "This study investigates whether tinodasertib can reverse ABCG2-dependent MDR in both two-dimensional (monolayer) cancer cell cultures and three-dimensional multicellular tumor spheroids." (PMID 40584625, 2025). "Therefore, ABCB1/ABCG2/ABCC1 are recognized as promising targets for the circumvention of MDR in cancer patients." (PMID 41328326, 2025). "This superfamily is composed of numerous pumps, including P-glycoprotein (also called ABCB1; its expression is detected in many cancers), multidrug resistance proteins (including ABCC1, or multidrug resistance-associated protein 1), and breast cancer resistance protein (BCRP/ABCG2)." (PMID 40869256, 2025).
cancer (continued). "Notably, MDR1 (ABCB1, P‐glycoprotein), MRP1 (ABCC1) and BCRP (ABCG2) are major transporters that mediate multidrug resistance in cancer cells by reducing intracellular drug concentrations, thereby diminishing the therapeutic effects of chemotherapeutic agents." (PMID 39877564, 2025). "Cytotoxicity observed in a long-term exposure of carcinoma-derived cell lines to an ENN mixture containing 19% ENN B was significantly reduced when breast cancer resistance protein (ABCG2) or P-glycoprotein (P-gp) were present, indicating that ENNs are substrates for these transport proteins." (PMID 40137953, 2025). "It is known that continuing smoking during the cancer treatments worsens the prognosis, possibly due to the fact that resistance to CS involves some of the same mechanisms, as the development of resistance to drugs, one of those being an increase in ABCG2." (PMID 38442133, 2024). "In addition, our recent study showed that USP24 stabilized ABCG2 and P‐gp to promote cancer cell drug resistance, implying that USP24 recognizes specific sequences or structures in ABC transporters, especially G family." (PMID 38140768, 2024). "Notably, irrespective of tissue origin, MTX-211 exhibited significantly diminished cytotoxicity in cancer cells expressing ABCG2." (PMID 38791198, 2024). "However, we noted the resistance to MTX-211 in cancer cells overexpressing ABCG2 alongside HEK293 cells ectopically expressing human ABCG2 (R482-HEK293), compared to parental HEK293 cells." (PMID 38791198, 2024). "We aimed to characterize the in vitro and in vivo interaction of ABCG2 with lumichrome, the main photodegradation product of riboflavin, which has proven in vitro anti-cancer activity and a therapeutical role in antibacterial photodynamic therapy as an efficient photosensitizer." (PMID 39337371, 2024). "Evidence suggests that a cooperative and potentially compensatory role for ABCB1 and ABCG2 in some cancers, using drugs that can target multiple transporters may provide additional benefits compared to single inhibition." (PMID 38254110, 2024). "In this type of cancer, improved OS was correlated with high ABCG2 expression only in early-stage cancer disease (stage 1) (p < 0.001), in high-grade tumors (G3) (p = 0.0.340), in patients who never smoked (p = 0.0220), and regardless of gender (p = 0.0400, p = 0.0021)." (PMID 39457707, 2024). "In addition, in both LUAD and LUSC, the hypomethylated ABCG2 promoter region was significantly less methylated in cancer samples than normal samples." (PMID 39457707, 2024). "Consequently, the higher levels of expression of ABCG2 frequently fosters the emergence of multidrug resistance (MDR) phenotypes in human cancer cells, leading to treatment inefficacy and relapse." (PMID 38791198, 2024). "Our findings revealed a notable decrease in the intracellular accumulation, efficacy, and cytotoxicity of MTX-211 in cancer cells with a high ABCG2 expression, a phenomenon that could be overcome by suppressing the activity of ABCG2." (PMID 38791198, 2024). "The human ATP‐binding cassette transporter subgroup G2 (ABCG2, also named BCRP) is expressed in different cancer cells and eliminates a broad spectrum of drugs, like doxorubicin, mitoxantrone and several tyrosine kinase inhibitors, from the cells by ATP‐depending efflux." (PMID 37727134, 2024). "In summary, we have identified a novel role for ABCG2 in cancer cell metabolism." (PMID 38641063, 2024). "ABCG2 is one of the most well-known molecules involved in drug resistance since it mediates the efflux of several drugs including doxorubicin, and is overexpressed in different pathophysiological mechanisms such as cancer progression and drug resistance." (PMID 39174500, 2024). "MTT assay was used to detect the reversal effect of RN486 on ABCG2-overexpressing cancer cells." (PMID 39081282, 2024). "In addition, ABCG2 is a marker of the side population (SP) cells, representing pluripotent cancer stem cells." (PMID 39457707, 2024).
cancer (continued). "Here, we discovered that the overexpression of the ATP-binding cassette (ABC) drug transporter ABCG2, a prevalent mechanism associated with multidrug resistance (MDR), could diminish the effectiveness of MTX-211 in human cancer cells." (PMID 38791198, 2024). "Breast cancer resistance protein (BCRP) transporter, encoded by the ABCG2 gene, is notably expressed in various tissues including the placenta, gastrointestinal system, brain, liver, breast, and cancer cells." (PMID 38731891, 2024). "In cancer cells, ABCG2 plays a critical role in promoting the multidrug resistance phenotype, as it actively enhances the efflux of chemotherapeutic agents, leading to decreased intracellular drug accumulation and a reduced efficacy of cancer treatments." (PMID 38542090, 2024). "The overexpression of ABCG2 associated with drug efflux may be among mechanisms of multidrug resistance (MDR), leading to failure in cancer therapy." (PMID 39457707, 2024). "Also, ABCG2 and P-gp have been shown to be frequently expressed in human cancer and act as xenobiotics efflux pumps to transport various classical chemotherapeutic agents out of cells." (PMID 39030572, 2024). "Understanding the role of ABCG2 in both cancer cells and blood vessels may help unravel the complexity of drug resistance and highlight the need for strategies that can bypass or inhibit ABCG2 function." (PMID 38542090, 2024). "Cigarette smoke has been shown to increase ABCG2 expression in diverse cancer cells." (PMID 38256106, 2024). "RN486 could be potentially used in conjunction with chemotherapy to alleviate MDR mediated by ABCG2 in cancer." (PMID 39081282, 2024). "The upregulation of ATP-binding cassette (ABC) transporters, such as ABCB1 (P-glycoprotein), ABCG2 (breast cancer resistance protein), and ABCC1 (multidrug resistance-associated protein), facilitates the efflux of 5-FU from cancer cells, diminishing its intracellular concentration and efficacy." (PMID 39000577, 2024). "Furthermore, it is important to point out that cancer stem cells express elevated levels of ABCG2 (subfamilies ABC transporters involved in multi-drug chemoresistance), and inhibition of ABCG2 can prevent multidrug resistance and selectively destroy CSCs." (PMID 39519572, 2024). "FTC is the first and widely known ABCG2 inhibitor to modulate drug resistance in cancer therapies." (PMID 39403604, 2024). "Furmonertinib, a novel third-generation EGFR-TKI, has shown promise in overcoming drug resistance mediated by the ATP-binding cassette transporters ABCB1 and ABCG2, which are central to the development of multidrug resistance in cancer patients receiving conventional chemotherapy." (PMID 39743996, 2024). "A positive correlation between cancer-associated fibroblast infiltration and ABCG2 expression was observed in LUAD, but not in LUSC." (PMID 39457707, 2024). "Additionally, the impact of MTX-211 on PI3K signaling and apoptosis was notably diminished in ABCG2-overexpressing S1-MI-80 cancer cell lines compared to their parental counterparts." (PMID 38791198, 2024). "Additionally, Sissung TM et.al (2010) reported that expression of ABCG2 provides resistance to 5-FU, and doxorubicin in various cancer cell types by expelling drugs outside and thus protecting them from apoptosis." (PMID 38347575, 2024). "ABCG2 is abundantly expressed on the membrane of EVs secreted by cancer cells." (PMID 39403600, 2024). "Indeed, a number of studies have shown that ABCG2 can protect cancer cells against stressors such as radiation, a function that cannot be explained by its role as a drug transporter." (PMID 38641063, 2024). "The findings presented here are consistent with the outcomes of the MDR reversal assay, which demonstrate that imperatorin has the ability to reinstate the sensitivity of cancer cells that overexpress ABCG2 by enhancing the intracellular accumulation of ABCG2 substrate drugs." (PMID 38004460, 2023).
cancer (continued). "In contrast, an increased level of ABCG2, and corresponding increase in E-cadherin, may induce circulating cancer cells to colonize at a distant site and form a metastatic tumour." (PMID 37445716, 2023). "Most of the analysed cancer types showed a downregulation of ABCG2 gene expression." (PMID 37445716, 2023). "Further links between Erα, ABCG2 and cancer stem cells still need to be determined." (PMID 36831452, 2023). "The in vitro incubation of the ABCG2 overexpressing cancer cells lines, H460/MX20 and S1-M1-80, with 0.3 μM of MK-2206 decreased the IC50 values of 1) mitoxantrone by 14.6 and 16.0-fold; 2) SN-38 by 8.5 and 2.2-fold and 3) topotecan by 9.7 and 2.8-fold, respectively." (PMID 37521473, 2023). "Overall, our findings suggest that furmonertinib effectively countered MDR in cancer cells overexpressing ABCB1 or ABCG2, achieved through the inhibition of drug efflux activity for both transporters, rather than by inducing changes in the protein expression of ABCB1 and ABCG2." (PMID 37762275, 2023). "Overexpression of the ABCG2 gene in cancer cells directly leads to MDR." (PMID 38002103, 2023). "In addition, our study showed that Fis and PTX inhibit ABCG2 drug efflux in cancer cells, ultimately reversing the MDR that is evident after initial chemotherapy treatments." (PMID 37990267, 2023). "ABCG2 expression was weaker in the normal mucosa than in cancer tissue." (PMID 37445716, 2023). "Therefore, the inhibition of ABCG2 activity during chemotherapy ought to improve the efficacy of the administered anti-cancer agents by reversing MDR or by enhancing the agents’ pharmacokinetic properties." (PMID 36678870, 2023). "Consequently, we investigated the interactions of furmonertinib with ABCB1 and ABCG2 in multidrug-resistant cancer cell lines." (PMID 37762275, 2023). "Drug efflux resistance mechanisms are characterized by the increased expression of ATP-binding cassette (ABC) transporters, such as ABCB1 (P-glycoprotein, MDR-1) or ABCG2 (BCRP), which are able to pump a variety of small molecules out of the cancer cell in an ATP dependent manner." (PMID 37567965, 2023). "ABCG2, an ATP-binding cassette transporter, extrudes hundreds of hydrophilic and hydrophobic compounds from cells, playing roles in xenobiotic clearance or multidrug resistance in cancer." (PMID 37596258, 2023). "ABCB1 and ABCG2 were first described as mediators of anticancer drug resistance in cancer cells." (PMID 36973040, 2023). "Breast cancer resistance protein (BCRP) or ABCG2 transporter is one of the most important ABC transporters implicated in MDR and the use of inhibitors is a promising approach to overcome the resistance in cancer." (PMID 38204967, 2023). "The increased expression of CD133, CD9, and CD44, along with SOX9, TUBB3, MGMT, and ABCG2, may have led the GBMs on a path of acquiring cancer-specific stemness." (PMID 36834653, 2023). "Consequently, patients with high ABCB1- or ABCG2-expressing multidrug-resistant tumors are usually insensitive to chemotherapy, resulting in cancer relapse and treatment failure." (PMID 37048130, 2023). "It has been shown that the activity of the 5-ATP-binding cassette transporter ABCG2 may affect the effectiveness of PDT by regulating the accumulation of porphyrins in cancer cells." (PMID 37759900, 2023). "While the causes of MDR in cancer are complex and involve multiple factors, it is commonly linked to the overexpression of two well-studied and characterized ATP-binding cassette (ABC) transporters ABCB1 (P-glycoprotein; MDR1) and ABCG2 (BCRP; MXR; ABCP)." (PMID 37762275, 2023). "The synergistic anchoring of TOX3 with WDR5 at the promoter of ABCG2 causes the enrichment of histone H3K4 tri-methylation, thereby further promoting ABCG2 transcription and expression and subsequent cancer stem-like traits expansion and drug sensitivity deregulation." (PMID 37708089, 2023).